IDUA (alpha-L-iduronidase)
Description:
Lysosomal hydrolase responsible for the degradation of the glycosaminoglycans heparan sulfate and dermatan sulfate.
Synonyms: MPS1; MPSI; IDA
Tractability: Small molecule: a structure with a bound ligand is known. Antibody: UniProt predicts a signal peptide or a membrane-spanning region. PROTAC: its protein half-life has been measured.
Target class: Enzyme; Hydrolase
Gene: Protein-coding gene on chromosome 4 (986,997 to 1,008,344, forward strand). Ensembl gene ENSG00000127415.
Subcellular location: Lysosome
Subcellular location (Human Protein Atlas): Vesicles
Pathways (Reactome):
Disease: MPS I - Hurler syndrome (CS/DS degradation); MPS I - Hurler syndrome (HS-GAG degradation)
Metabolism: CS/DS degradation; HS-GAG degradation
Gene Ontology:
Molecular function: L-iduronidase activity; hydrolase activity, hydrolyzing O-glycosyl compounds; signaling receptor binding
Biological process: dermatan sulfate proteoglycan catabolic process; heparin proteoglycan catabolic process; disaccharide metabolic process; heparan sulfate proteoglycan catabolic process; carbohydrate metabolic process; glycosaminoglycan catabolic process
Cellular component: extracellular exosome; lysosomal lumen; lysosome
Genetic constraint (gnomAD): Loss-of-function variants: 64 observed, 58.63 expected, observed/expected ratio (o/e) 1.09, 90% interval 0.89 to 1.34. The synonymous counts are far from expectation, so gnomAD's model fits this gene poorly and the ratio says little. Missense variants: 1,046 observed, 795.69 expected, observed/expected ratio (o/e) 1.31, 90% interval 1.25 to 1.38. Synonymous variants: 529 observed, 369.55 expected, observed/expected ratio (o/e) 1.43, 90% interval 1.33 to 1.54.
Gene-disease validity (ClinGen):
ClinGen rates the evidence that IDUA causes each of these diseases.
mucopolysaccharidosis type 1 (autosomal recessive): Definitive. The most common type of mucopolysaccharidosis.
Homologues: Orthologues: chimpanzee IDUA (99% identical), macaque IDUA (96% identical), pig IDUA (82% identical), dog IDUA (82% identical), guinea pig IDUA (81% identical), mouse Idua (78% identical), rat Idua (77% identical), zebrafish idua (54% identical), tropical clawed frog idua (53% identical), Drosophila melanogaster Idua (28% identical).
Diseases named in the same sentence as IDUA in open-access papers:
IDUA is named in the same sentence as 65 diseases in open-access papers, as found by Europe PMC text mining. Sharing a sentence is not in itself a finding about the gene and the disease. The quoted sentences say what the papers report.
mucopolysaccharidosis type 1 (88 papers, 2009 to 2026). "Mucopolysaccharidosis type I (MPS I) is an inherited lysosomal storage disorder (LSD) caused by recessive mutations in the α-L-iduronidase (IDUA) gene." (PMID 40251406, 2025). "Mucopolysaccharidosis type I (MPS I) is a lysosomal illness caused by a deficiency of the enzyme alpha-L-iduronidase (IDUA), which is necessary for the breakdown of the glycosaminoglycans, dermatan, and heparan sulphate." (PMID 40573317, 2025). "Mucopolysaccharidosis type I (MPS I) is a recessive inherited disorder due to mutations in the IDUA (alpha-L-iduronidase) gene located in chromosome 4p16.3." (PMID 41226457, 2025). "Mucopolysaccharidosis type I (MPS I) is an inherited lysosomal storage disorder caused by mutations in the IDUA gene and is classified into three forms according to severity: Hurler disease, Hurler/Scheie disease, and Scheie disease." (PMID 40251406, 2025). "Schuh and colleagues administered nanoemulsions complexed with a plasmid encoding the IDUA (alpha-L-iduronidase) protein via nasal delivery, aiming to reach the brain for mucopolysaccharidosis type I (MPS I) gene therapy." (PMID 41012513, 2025). "Mucopolysaccharidosis type I (MPS I) is a rare autosomal recessive lysosomal storage disease (LSD) linked to pathogenic variants in IDUA gene." (PMID 39754079, 2025). "Mucopolysaccharidosis type I (MPS I) is an autosomal recessive lysosomal disorder caused by mutations in the α-L-iduronidase (IDUA) gene, which encodes the enzyme responsible for glycosaminoglycan (GAG) catabolism." (PMID 40910004, 2025). "Mucopolysaccharidosis type I (MPS I) is caused by mutations in the gene encoding α-L-iduronidase (IDUA)." (PMID 41163043, 2025). "Genetic deficiency of alpha-L-iduronidase causes mucopolysaccharidosis type I (MPS-I) disease, due to accumulation of glycosaminoglycans (GAGs) including chondroitin/dermatan sulfate (CS/DS) and heparan sulfate (HS) in cells." (PMID 38760939, 2024). "Mucopolysaccharidosis type I (MPS I) is a rare metabolic disorder caused by deficiency of α-L-iduronidase (IDUA), resulting in glycosaminoglycan (GAG) accumulation and multisystemic disease." (PMID 39687731, 2024). "Mucopolysaccharidosis type 1 (MPS I) is an autosomal recessive lysosomal disorder caused by deficiency of the enzyme α-L-iduronidase (IDUA) resulting in an accumulation of the glycosaminoglycans (GAG) heparan sulfate and dermatan sulfate." (PMID 39687731, 2024). "Mucopolysaccharidosis type I (MPS I) is an autosomal recessive lysosomal storage disease (LSD) associated with deficient activity of α-L-iduronidase (IDUA; EC 3.2.1.76)." (PMID 39272740, 2024). "Mucopolysaccharidosis type I (MPS I) is an inherited lysosomal disease caused by lowered activity of the enzyme alpha-L-iduronidase (IDUA)." (PMID 38768102, 2024). "MPS I, or Hurler syndrome, is an autosomal recessive disorder caused by mutations in the IDUA gene that leads to IDUA deficiency." (PMID 36678838, 2023). "Mucopolysaccharidosis type I is an AR LSD due to mutation of the gene encoding alpha-L-iduronidase (IDUA) on chromosome 4p16." (PMID 37239976, 2023). "Mutations in the IDUA gene cause mucopolysaccharidosis I (MPS I) due to a deficiency of a-L-iduronidase (IDUA) that leads to defective catabolism of the glycosaminoglycans such as heparan and dermatan sulphate." (PMID 38248833, 2023). "This concept was introduced decades ago and very recently it was tested in a mouse model of human lysosomal storage disease, the mucopolysaccharidosis type I (MPS I) caused by α-L-iduronidase (IDUA) enzymatic activity deficiency." (PMID 37304036, 2023). "Deficiency of IDUA enzymatic activity causes undegraded DS and HS to accumulate in multiple tissues, leading to organ dysfunction knownas mucopolysaccharidosis type I (MPS I)." (PMID 38250526, 2023). "Mucopolysaccharidosis type I (MPS I) is caused by alpha-L-iduronidase deficiency encoded by the IDUA gene." (PMID 35073349, 2022).
mucopolysaccharidosis type 1 (continued). "Mucopolysaccharidosis type I (MPSI) (OMIM #252800) is an autosomal recessive disorder caused by pathogenic variants in the IDUA gene encoding for the lysosomal alpha-L-iduronidase enzyme." (PMID 36232472, 2022). "Mucopolysaccharidosis type I (MPS I) is caused by a deficiency of the lysosomal hydroxylase alpha-l-iduronidase (IDUA)." (PMID 34054689, 2021). "The closely related disease mucopolysaccharidosis type I (MPS I) is caused by deficiency of the lysosomal enzyme iduronidase (IDUA), catalyzing step two in the degradation of HS and DS." (PMID 34360653, 2021). "Mucopolysaccharidosis type I (MPS I) is caused by deficiency of the enzyme α-L-iduronidase (IDUA) and has a disease spectrum that ranges from mild to severe." (PMID 34040503, 2021). "Mucopolysaccharidosis type I (MPS I) is a rare autosomal recessive disorder caused by deleterious mutations in the α-L-iduronidase (IDUA) gene." (PMID 34833038, 2021). "Those affected with MPS I have an alpha-L-iduronidase (IDUA) deficiency resulting in glycosaminoglycan (GAG) accumulation within lysosomes, primarily dermatan and heparin sulfates." (PMID 32121123, 2020). "Mucopolysaccharidosis type I (MPS I) is a rare autosomal storage disorder resulting from the defective alpha‐L‐iduronidase (encoded by IDUA) enzyme activity and accumulation of glycosaminoglycans (GAGs) in lysosomes." (PMID 31758674, 2020). "Mucopolysaccharidosis type I (MPSI) is a rare autosomal recessive disorder caused by a deficiency of α‐l‐iduronidase (IDUA) encoded by the IDUA gene." (PMID 31386236, 2019). "Mucopolysaccharidosis Type I (MPS I) is a rare genetic lysosomal storage disease caused by a mutation of IDUA gene." (PMID 31834922, 2019). "Mucopolysaccharidosis type I (MPS I) is a severe disease due to deficiency of the lysosomal hydrolase α-L-iduronidase (IDUA) and the subsequent accumulation of the glycosaminoglycans (GAG), leading to progressive, systemic disease and a shortened lifespan." (PMID 30528089, 2019). "The alpha‐L‐iduronidase (IDUA) is a complex human glycoprotein which deficiency leads to the development of the mucopolysaccharidosis type I (MPS I), a progressive lysosomal storage disorder." (PMID 30058762, 2019). "Mucopolysaccharidosis type I (MPS I) is caused by a deficiency of alpha-l-iduronidase (IDUA) and storage of HS and dermatan sulfate (DS)." (PMID 30442188, 2018). "Mucopolysaccharidosis type I (MPS I) is an autosomal recessive lysosomal storage disorder caused by the deficient activity of the enzyme α-L-iduronidase (IDUA, EC 3.2.1.76)." (PMID 29843745, 2018). "Mucopolysaccharidosis type I (MPS I) is a debilitating hereditary disease characterized by alpha-L-iduronidase (IDUA) deficiency and consequent inability to degrade glycosaminoglycans." (PMID 28595620, 2017). "Mucopolysaccharidosis type I (MPS I) is an autosomal recessive disease due to deficiency of α-L-iduronidase (IDUA), a lysosomal enzyme that degrades glycosaminoglycans (GAG) heparan and dermatan sulfate." (PMID 28676128, 2017). "Mucopolysaccharidosis type I (MPS I) is caused by the deficiency of alpha-L-iduronidase (IDUA), which is involved in the degradation of glycosaminoglycans (GAGs), such as heparan sulfate and dermatan sulfate in the lysosome." (PMID 26407983, 2015). "Mucopolysaccharidosis type I (MPS I) is an autosomal recessive lysosomal storage disorder caused by a deficiency of the lysosomal hydrolase α-L-iduronidase (IDUA)." (PMID 24088413, 2013). "Mucopolysaccharidosis type I (MPS I) is a progressive multisystem lysosomal storage disease caused by deficiency of the enzyme α-L-iduronidase (IDUA)." (PMID 23837464, 2013). "Mucopolysaccharidosis type I (MPS I) is an autosomal recessive lysosomal storage disorder caused by the deficient activity of the enzyme of α-L-iduronidase (IDUA, EC 3.2.1.76)." (PMID 21639919, 2011).
mucopolysaccharidosis type 1 (continued). "Mucopolysaccharidosis type I is caused by a deficiency of the glycosidase alpha-L-iduronidase (α-L-iduronidase iduronohydrolase, EC 3.2.1.76; IDUA) and the resulting accumulation of undergraded dermatan sulfate and heparan sulfate." (PMID 22074387, 2011). "Mucopolysaccharidosis type I (MPS I) is an autosomal recessive lysosomal storage disorder caused by a genetic defect in alpha-L-iduronidase (IDUA) which is involved in the degradation of dermatan and heparan sulfates." (PMID 21521498, 2011). "Mucopolysaccharidosis type I (MPS I) is an autosomal recessive lysosomal storage disorder that results from a deficiency in the alpha-L-iduronidase (IDUA; E.C.3.2.1.76)." (PMID 21521498, 2011). "We also detected a novel missense mutation of the IDUA gene, c.826G>A (p.E276K) causing Scheie syndrome." (PMID 21364962, 2011). "Mucopolysaccharidosis type I (MPS I) is an autosomal recessive lysosomal storage disorder which is caused by a deficiency of the enzyme α-l-iduronidase (IDUA, EC 3.2.1.76; OMIM *252800)." (PMID 19396826, 2009). "MPS I (Mucopolysaccharidosis type I) is a rare lysosomal storage disease originating from the deficiency of the enzyme alpha-L-iduronidase, encoded by the IDUA gene, which impairs the degradation of glycosaminoglycans (GAGs) and diminishes biological functioning across several organs." (PMID 40573317, 2025). "Mucopolysaccharidosis type I (MPS I) is an autosomal recessive lysosomal storage disorder characterized by deficient or absent α-L-iduronidase (IDUA) enzyme activity due to pathogenic variants in the IDUA gene." (PMID 39077064, 2024). "Mucopolysaccharidosis type I (MPS-I) is a rare lysosomal storage disorder caused by deficiency of the enzyme alpha-L-iduronidase, which removes iduronic acid in both chondroitin/dermatan sulfate (CS/DS) and heparan sulfate (HS) and thereby contributes to the catabolism of glycosaminoglycans (GAGs)." (PMID 34192316, 2021). "Mucopolysaccharidosis type I (MPS I) includes Hurler syndrome, Hurler–Scheie syndrome, and Scheie syndromes that are caused by homozygous or compound heterozygous mutations in alpha-l-iduronidase (IDUA) gene that result in developmental abnormalities and intellectual disability." (PMID 33996898, 2021). "Mucopolysaccharidosis type I (MPS I) is a lysosomal storage disease caused by a mutation in the IDUA gene that manifests as central nervous system (cognitive impairment) and somatic (eg, bone, cartilage, heart, liver) abnormalities that vary broadly in severity." (PMID 33728251, 2021). "Mucopolysaccharidosis type I (MPS I) is an autosomal recessive lysosomal disorder which originates from a deficiency in α-L-iduronidase (IDUA), an enzyme required for the proper degradation of two glycosaminoglycans (GAG)—namely, dermatan and heparan sulfate (HS)." (PMID 33573213, 2021). "The most severe of all is mucopolysaccharidosis type 1 (MPS1), also known as Hurler syndrome, caused by a defective form of alpha-L-iduronidase (IDUA)." (PMID 36361918, 2022). "Mucopolysaccharidosis type I (MPS I) is an inherited metabolic disorder caused by deficiency of the lysosomal enzyme alpha-L-iduronidase (IDUA)." (PMID 34040503, 2021). "Mucopolysaccharidosis type I (MPS I) is an autosomal recessive disorder characterized by deficiency of alpha-L-iduronidase (IDUA) and consequently inability to degrade glycosaminoglycan (GAG)." (PMID 28595620, 2017). "Mucopolysaccharidosis type I (MPS I) is an autosomal recessive disease caused by deficient activity of alpha-L-iduronidase." (PMID 28859139, 2017). "Mucopolysaccharidosis type I (MPS I) is a genetic disease caused by the deficiency of α-L-iduronidase (IDUA) activity." (PMID 24053568, 2013). "Mucopolysaccharidosis type I (MPS I) is an autosomal recessive lysosomal storage disorder that is caused by a deficiency of the enzyme α-l-iduronidase (IDUA)." (PMID 19396826, 2009).
mucopolysaccharidosis type 1 (continued). "Pompe disease (Glycogen Storage Disease type II, α-glucosidase deficiency), and Mucopolysaccharidosis Type I (MPS-I) (Hurler, Hurler/Scheie or Scheie Disease) are caused by a deficiency of α-glucosidase and alpha-L-iduronidase, respectively." (PMID 41272769, 2025). "Mucopolysaccharidosis I (MPS I, Hurler syndrome) is an autosomal recessive condition caused by mutations in the IDUA gene, which leads to a deficiency in alpha-L-iduronidase." (PMID 39940729, 2025). "Mutations in IDUA and HGSNAT cause mucopolysaccharidosis I and III types, respectively; mutations in ARSA cause metachromatic leukodystrophy (MLD) that belongs to the sphingolipidosis group." (PMID 38248833, 2023). "Mucopolysaccharidosis type I (MPS I) is a severe metabolic disorder caused by deficiency of the lysosomal enzyme, α-L-iduronidase (IDUA), which can catalyze the degradation of glycosaminoglycans (GAGs) heparan and dermatan sulfates." (PMID 36813914, 2023). "Mucopolysaccharidosis type I (MPSI) is a lysosomal overload disease related to the deficiency of a glycosaminoglycan (GAG) metabolism enzyme, alpha-L-Iduronidase (IDUA)." (PMID 35465368, 2022). "Mucopolysaccharidosis type I (MPS I) is an autosomal recessive disease caused by the deficiency of alpha-L-iduronidase (IDUA; EC 3.2.1.76), an enzyme coded by the IDUA gene." (PMID 35073349, 2022). "Another LSD is Mucopolysaccharidosis type I (MPS I), caused by deficiency of IDUA (alpha-L-iduronidase), which leads to the ubiquitous accumulation of two glycosaminoglycans (GAGs), dermatan, and heparan sulfates." (PMID 36230953, 2022). "Mucopolysaccharidosis type I (MPS I, OMIM 252800) is a lysosomal storage disorder (LSD) caused by a deficiency of α-L-iduronidase (IDUA), which is a lysosomal hydrolase involved in glycosaminoglycans (GAG) catabolism." (PMID 36613977, 2022). "Mucopolysaccharidosis type 1 (MPS I, also referred to as Hurler syndrome; OMIM #607014) is caused by deficiency of the lysosomal hydrolase alpha-l-iduronidase (IDUA, EC3.2.1.76), which leads to the accumulation of dermatan sulfate and heparan sulfate." (PMID 34054689, 2021). "Mucopolysaccharidosis type I (MPS I) is a lysosomal disease, caused by a deficiency of the enzyme alpha-L-iduronidase (IDUA)." (PMID 33572941, 2021). "Mucopolysaccharidosis I (MPS I) results from a deficiency of a lysosomal enzyme, alpha-L-iduronidase (IDUA)." (PMID 32121123, 2020). "Mucopolysaccharidosis I (MPS I) is a rare disease that occurs in dogs and humans due to a deficiency of the lysosomal enzyme, alpha-L-iduronidase." (PMID 32121123, 2020). "The lysosomal storage disorder, mucopolysaccharidosis I (MPSI), results from mutations in IDUA, the gene that encodes the glycosaminoglycan-degrading enzyme α-L-iduronidase." (PMID 33198351, 2020). "Mucopolysaccharidosis type I (MPS I, OMIM#252800), an autosomal alpha‐L‐iduronidase (IDUA, EC 3.2.1.76) deficiency, resulting from IDUA (NG_008103.1) mutations affects the enzyme activity of alpha‐L‐iduronidase." (PMID 31758674, 2020). "Mucopolysaccharidosis type I (MPS I) is a rare autosomal recessive disorder, caused by deficiency of the enzyme α-L-iduronidase (IDUA), which is required for the lysosomal degradation of the glycosaminoglycans (GAGs) dermatan and heparan sulfate." (PMID 30528089, 2019). "Mucopolysaccharidosis type 1 (MPS-1), also known as Hurler's disease, is a congenital metabolic disorder caused by a mutation in the alpha-L-iduronidase (IDUA) gene, which results in the loss of lysosomal enzyme function for the degradation of glycosaminoglycans." (PMID 31065277, 2019). "Mucopolysaccharidosis type I (MPS I) is a life-threatening, autosomal recessive disease caused by deficiency of α-L-iduronidase (IDUA), a lysosomal enzyme responsible for metabolizing the glycosaminoglycans (GAGs) dermatan and heparan sulfate." (PMID 30419879, 2018).